TBX1 (T-box transcription factor 1)
Diseases named in the same sentence as TBX1 in open-access papers (continued):
Sharing a sentence is not in itself a finding about the gene and the disease.
schizophrenia (10 papers, 2005 to 2025). A major psychotic disorder characterized by abnormalities in the perception or expression of reality. "A recent large-scale exome sequencing identified an ultra rare protein-truncating variant of TBX1 among individuals with schizophrenia, but its statistical significance is unclear due to power limitation." (PMID 34737458, 2022). "We searched for mutations in the TBX1 gene in 652 patients with schizophrenia and 567 control subjects using a re-sequencing method and conducted a reporter gene assay." (PMID 27879657, 2016). "Taken together, these studies suggest that the TBX1 gene is likely a common susceptible gene among several mental disorders such as schizophrenia, autism, and mental retardation." (PMID 27879657, 2016). "Mutations and haploinsufficiency of the TBX1 gene are sufficient to cause reduced prepulse inhibition, a behavioral abnormality that is associated with schizophrenia endophenotype." (PMID 27879657, 2016). "Heterozygous pathogenic variants in PRODH have been associated with an increased risk of schizophrenia, and proximal deletions excluding TBX1 but showing syndromic features (particularly neurological ones) have suggested candidate genes such as DGCR6 (OMIM *601279) and PRODH." (PMID 41165438, 2025). "Haploinsufficiency of the TBX1 gene is associated with schizophrenia endophenotype." (PMID 27879657, 2016). "Here, we aimed to examine whether there are common or rare genetic variants of the TBX1 gene associated with schizophrenia." (PMID 27879657, 2016). "Our findings suggest that the TBX1 gene is unlikely a major susceptible gene for schizophrenia in an ethnic Chinese population for Taiwan, but a few rare mutations in the TBX1 gene may contribute to the pathogenesis of schizophrenia in some patients." (PMID 27879657, 2016). "We identified a total of 31 genetic variants of the TBX1 gene in patients with schizophrenia and control subjects, including six common SNPs (rs737868, rs41298814, rs2301558, rs72646967, rs4819522, and rs5746826) with minor allele frequency (MAF) above 5% and 25 rare mutations with MAF below 5%." (PMID 27879657, 2016). "However, no increasing burden of rare mutations was found in the patient group, suggesting rare mutations of the TBX1 gene occurred equally in both patients with schizophrenia and control groups." (PMID 27879657, 2016). "This study aimed to investigate whether the TBX1 gene is associated with schizophrenia." (PMID 27879657, 2016). "Ultrarare variants of TBX1 (which encodes T-box transcription factor 1) are found in individuals with ASD and schizophrenia." (PMID 37461714, 2023). "In our study, we identified two schizophrenia-specific variants (c.-123G>C and c.-11delC) with abnormal promoter activity, suggesting that abnormal TBX1 gene expression may contribute to the pathogenesis of schizophrenia in some patients." (PMID 27879657, 2016). "To test this possibility, we systemically searched for genetic variants in all the exons of the TBX1 gene in a sample of patients with schizophrenia and control subjects from Taiwan and conducted a reporter gene activity assay to characterize genetic variants located at 5′ UTR of the TBX1 gene." (PMID 27879657, 2016). "Notably, we identified two rare schizophrenia-specific mutations (c.-123G>C and c.-11delC) located at 5′ UTR of the TBX1 gene." (PMID 27879657, 2016). "There is a report examining whether or not the TBX1 gene is associated with schizophrenia, and results suggest that a couple of rare mutations in the TBX1 gene may contribute to the patho-genesis of schizophrenia in some patients." (PMID 36676170, 2023). "This study suggests that the common genetic variants of the TBX1 gene may not play a major role in conferring susceptibility to schizophrenia." (PMID 27879657, 2016).
schizophrenia (continued). "Taken together, our findings open a new window for investigating the potential substrates of altered cognitive speed in carriers of TBX1 SNVs, 22q11.2, and other CNVs, and in idiopathic cases of ASD and schizophrenia." (PMID 34737458, 2022). "Therefore, it is plausible that the deletion or disruption of the TBX1 gene may alter the expression of genes required for proper development and function of neuronal circuits in the central nerve system, and eventually lead to the formation of schizophrenia." (PMID 27879657, 2016). "A murine model overexpressing the mouse orthologs of several genes in this region (CDCrel, GP1Bβ, TBX1 and WDR14) exhibits behavioral abnormalities consistent with schizophrenia traits." (PMID 18284679, 2008).
autism (9 papers, 2011 to 2023). Persistent deficits in social interaction and communication and interaction as well as a markedly restricted repertoire of activity and interest as well as repetitive patterns of behavior. "CNVs disrupt several genes associated with SCZ, including TBX1 (also associated with autism), ERBB4 (encodes a receptor for NDF/heregulin), SLC1A3 (a glutamate transporter), RAPGEF4 (a nucleotide exchange factor), and CIT (a neuronal Rho-target gene)." (PMID 37486921, 2023). "Genetic factors related to autism include TBX1 (involved in the regulation of development and associated with the 22q11.2 deletion syndrome), SHANK3 (a synaptic scaffolding gene), NLGN4 (a neuroligin gene), PCDH10 (a protocadherin gene), and NHE9." (PMID 37486921, 2023). "In addition, PAK2/Pak within 3q29, TBX1/org-1 within 22q11.2, autism-associated CHD8/kis, and microcephaly-associated ASPM/asp also showed smaller wing areas and vein lengths." (PMID 32579612, 2020). "Indeed, a genetic model of autism, known as the Tbx1 heterozygous (HT) mice in which the mutated Tbx1 gene is part of the chromosome region 22q11.2 in humans, has shown a decreased T-maze spontaneous alternation along with ASD-related social interaction and ultrasonic vocalization impairments." (PMID 26837496, 2016). "The importance of this region in autism has been recently highlighted by the identification of two autism candidate genes, TBX1 and GNB1L." (PMID 23840741, 2013). "In addition, mouse pups' USVs also contained the specific call transition pattern, and the pattern was different between wildtype B6 and the genetic model of autism of TBX1 pups." (PMID 34248780, 2021). "Congenic TBX1 heterozygous mice displayed the autism-related behavioral phenotypes." (PMID 27879657, 2016). "In fact, one individual carrying a 16p11.2 deletion with autism and features of ID also has a maternally inherited 22q11.2 duplication (TBX1) providing further evidence for the two-hit hypothesis we previously proposed for severe developmental delay." (PMID 22102821, 2011). "The Decipher database lists 16 variations containing the TBX1 gene and associated with autistic disorder; for SFARI Gene database, TBX1 is a known “syndromic” gene; moreover, there is also a linkage study (International Molecular Genetic Study of Autism Consortium, 1998) that associates the chr." (PMID 37186221, 2023).
congenital heart disease (9 papers, 2013 to 2024). A heart disease that is present at birth. "P4 on the other hand also had a TBX1 variant but had congenital heart defects and TCL that later normalized." (PMID 34539671, 2021).
cleft palate (7 papers, 2013 to 2023). Cleft palate is a fissure type embryopathy that affects the soft and hard palate to varying degrees. "Many genes lie within the deleted region, of which only Tbx1 has been linked to cleft palate." (PMID 28420997, 2017). "Tbx1 loss- and gain-of-function result in cleft palate in human DGS patients and mouse models." (PMID 24068957, 2013). "Ablation of Tbx1, which is expressed in the epithelium of the palatal shelves, results in abnormal intraoral epithelial fusions between the palatal shelves and the mandible, resulting in various degrees of the cleft palate phenotype (complete, incomplete, and submucosal cleft palate)." (PMID 35645294, 2022). "However, it requires a homozygous deletion of Tbx1 for mice to develop a cleft palate, suggesting that other genes in the deleted 22q11.2 region—such as Dgcr8—might also contribute to the cleft palate observed with the syndrome." (PMID 28420997, 2017). "This is not unique among 22q11DS candidate genes; Tbx1 null mice also have cleft palates." (PMID 36790128, 2023).
Hypocalcemia (7 papers, 2014 to 2025). An abnormally decreased calcium concentration in the blood. "Craniofacial features in groups 1+2 and hypocalcemia in group 1 are well explained by the TBX1 mutation." (PMID 24637876, 2014). "The patient with an intragenic TBX1 deletion (ID 48) presented pulmonary stenosis, primary immunodeficiency, moderate intellectual disability, hypocalcemia, microcephaly, hypermetropia, emotional lability, and facial dysmorphism." (PMID 41165438, 2025). "In addition to craniofacial features with and without hypocalcemia, TBX1 mutation positive subject II-2 had sensorineural deafness, and III-5 had Graves' disease." (PMID 24637876, 2014).
hypoparathyroidism (7 papers, 2014 to 2024). Hypoparathyroidism is an endocrine disorder in which the parathyroid glands in the neck do not produce enough parathyroid hormone (PTH). "The congenital malformations of heart defect, hypoplasia of the thymus, and hypoparathyroidism are often linked to the haploinsufficiency of the TBX1 gene." (PMID 37013615, 2023).
CHARGE syndrome (6 papers, 2016 to 2023). CHARGE syndrome is a multiple congenital anomaly syndrome characterized by the variable combination of multiple anomalies, mainly Coloboma; Choanal atresia/stenosis; Cranial nerve dysfunction; Characteristic ear anomalies (known as the major 4 C's). "It has been postulated that a functional interaction between CHD7, TBX1 and RA signaling could explain the phenotypic overlap in DGS due to CHARGE syndrome, 22q11.2del, TBX1 deficiency, and RA embryopathy." (PMID 33257998, 2021).
ventricular septal defect (6 papers, 2016 to 2025). The presence of a defect (opening) in the septum that separates the two ventricles of the heart. "Knockout mice for Tbx1 or double heterozygous knockout mice for Gata4 and Gata6 exhibit fetal nuchal edema with ventricular septal defect (VSD) and persistent truncus arteriosus (PTA)." (PMID 36111337, 2022). "Deletions affecting the TBX1 gene in the 22q11.2 region are strongly linked to Tetralogy of Fallot (TOF) a complex defect involving pulmonary stenosis, right ventricular hypertrophy, aortic overhang, and ventricular septal defect (VSD)." (PMID 39925442, 2025). "Most but not all had an accompanying ventricular septal defect (VSD; n = 30), in contrast to Tbx1-/- mutant embryos, which all has a PTA with a VSD." (PMID 28346476, 2017).
breast carcinoma (5 papers, 2014 to 2022). "We imputed expressions of seven genes other than TBX1 and LOXL2 and showed that these genes were associated with breast cancer risk in either the ABCC or BCAC data at P < 0.05." (PMID 32139696, 2020). "TBX1 gene has been reported to be hypermethylated in breast cancer and PCa." (PMID 33575219, 2020). "Inhibition of the miR-200b-200a-429 promoter by ZEB2 was rescued by TBX1 in a dose-dependent manner in these cells, but not in MCF7 breast cancer cells." (PMID 36418889, 2022).
developmental delay (5 papers, 2009 to 2025). "A report links mutation in the TBX1 gene to developmental delay." (PMID 27879657, 2016).
immune deficiency (5 papers, 2014 to 2025). "Among the genes that impact midline development generally, the most well-known association with immune deficiency is T-Box Transcription Factor 1 (TBX1)." (PMID 33987750, 2021). "Combined immunodeficiencies alongside syndromic characteristics were associated with pathogenic mutations in DOCK8, STAT3, WAS, ATM, and TBX1, which included an autosomal dominant STAT3 variant (c.1144C>T; p.Arg382Trp) and an X-linked WAS variant (c.271C>T)." (PMID 40806973, 2025). "This deletion does not affect the DGS critical genes HIRA and TBX1; however, immune deficiency and recurrent infections have been described for this region." (PMID 35486341, 2022). "However, evaluation of inheritance is limited because specific tbx-1 mutations and multifactorial associations that predict severe immunodeficiency have not been established." (PMID 24996427, 2014).
parathyroid tumors (5 papers, 2018 to 2023). "In bladder urothelial carcinoma, TBX1 was up-regulated and contributed to a better prognosis of patients, while in the parathyroid tumor, TBX1-expressing cells were markedly reduced, and TBX1 deficiency potentially contributed to the low proliferative nature of tumors." (PMID 33557670, 2021). "In a recent study, dysregulated TBX1 level has been associated with parathyroid tumor model." (PMID 30209892, 2018). "TBX1 deficiency may potentially contribute to the low proliferative index of parathyroid tumors." (PMID 31750236, 2019). "For instance, TBX1 expression was down-regulated in parathyroid tumor and thyroid cancer, while in basal cell carcinoma, TBX1 was highly expressed." (PMID 33557670, 2021). "Conversely, TBX1 exerted pro-oncogenic functions in parathyroid tumor and basal cell carcinoma." (PMID 33557670, 2021).
Tetralogy of Fallot (5 papers, 2017 to 2025). A congenital cardiac malformation comprising pulmonary stenosis, overriding aorta, ventricular septum defect, and right ventricular hypertrophy. "As such, some DS heart defects, such as the tetralogy of Fallot observed in some individuals, may be related to Ripply3-dependent downregulation of Tbx1, whereas in DGS, they are caused by the direct Tbx1 haploinsufficiency." (PMID 40982554, 2025). "Mutations in NKX2-5 (5q35.1), GATA4 (8q23.1), ZFPM2 (8q23.1), GATA6 (18q11.2), GDF1 (19p13.11), JAG1 (20p12.2), and TBX1 (22q11.21) have been reported in sporadic cases with tetralogy of Fallot; however, interaction of these genes and FMR1 gene has never been reported." (PMID 28751920, 2017). "TBX1 is considered a candidate gene of DGS/VCFS because haploinsufficiency of TBX1 leads to the typical phenotypes of DGS/VCFS, conotruncal anomaly face syndrome (OMIM #217095), and tetralogy of Fallot (OMIM #187500)." (PMID 35645294, 2022).
basal cell carcinoma (4 papers, 2016 to 2024). A carcinoma involving the basal cells. "Also of interest is the strong significance for a basal cell carcinoma pathway because Tbx1 has been recently implicated in this type of tumour." (PMID 27256596, 2016). "For example, TBX1 plays a tumor-promoting role in basal cell carcinoma and TBX3 plays a tumor-promoting role in basal cell carcinoma in HCC, melanocytoma, and bladder cancer, whereas TBX1 and TBX3 exert a tumor-suppressing effect on thyroid cancer and fibrosarcoma, respectively." (PMID 38965548, 2024).
deafness (4 papers, 2014 to 2023). An inherited or acquired condition characterized by the complete loss of the ability to hear from one or both ears. "In addition, we identified potentially novel deafness-associated genes Mpzl2 in IMCs and Tbx1 in MCs along with the known deafness-associated genes in IMCs (Kcnj10, Met, Mitf, Gjb6, Ednrb, and Gjb2) and in MCs (Kcnq1, Esrrb, Kcne1, Lrp2, Slc22a4, and Hgf)." (PMID 37322474, 2023).
depression (4 papers, 2020 to 2025). "In addition, combined with previous genome-wide association studies on depression, a correlation was found between the levels of Tnni3k and Tbx1 in the hippocampus and RIB induced depressive-like behavior." (PMID 33531473, 2021). "Only four SNV variants were considered to have high penetrance for depression: OGDHL rs2293239, TBX1 rs41298838, IL16 rs201457933, and FBXO15 rs79499419." (PMID 35370858, 2022). "Compared with TBX1, IL-16, and FBXO15, we found that OGDHL was strongly associated with depressive disorders in a range of different aspects." (PMID 35370858, 2022).
thyroid cancer (4 papers, 2020 to 2024). "TBX1 promoter methylation in thyroid cancer results in the downregulation of TBX1 expression, promoting cancer progression." (PMID 38965548, 2024). "In thyroid cancer, TBX1 exerted its tumor suppressor function through inhibiting phosphorylation of AKT and ERK." (PMID 33557670, 2021). "In thyroid cancer, the up-regulation of TBX1 remarkably inhibited cell proliferation and metastasis and tumorigenic potential in mice, and promoted cell apoptosis." (PMID 33557670, 2021). "TBX1 is frequently inactivated by promoter methylation and inhibits thyroid cancer growth by inhibiting the PI3K/AKT and MAPK/ERK signaling pathways." (PMID 33575219, 2020). "Furthermore, overexpression of TBX1 significantly suppressed cell viability and tumorigenic potential in thyroid cancer cells of nude mice." (PMID 38965548, 2024). "Interestingly, TBX1 methylation is significantly correlated with gender, explaining to some extent the higher incidence of thyroid cancer in women." (PMID 38965548, 2024). "In thyroid cancer, TBX1 was identified as a tumor-suppressive gene." (PMID 33557670, 2021). "TBX1 downregulates the expression of matrix metalloproteinases (MMPs), exerting a EMT-inhibitory effect in thyroid cancer cells." (PMID 38965548, 2024). "TBX1 was also observed to inhibit tumor development by regulating the PI3K/AKT and MAPK/ERK signaling pathways in human thyroid cancer." (PMID 33557670, 2021).
Anxiety (3 papers, 2018 to 2026). Intense feelings of nervousness, tension, or panic often arise in response to interpersonal stresses. "No significant phenotypic abnormalities were observed in conditional PdgfrαCre;Tbx1+/flox mice regarding neonatal ultrasonic vocalizations, social interaction, novel object approach, anxiety-like behavior (elevated plus maze), or open-field locomotion and thigmotaxis." (PMID 42163352, 2026).
athymia (3 papers, 2009 to 2022). "We present a patient with early diagnosis of congenital athymia due to TBX1 haploinsufficiency." (PMID 35095830, 2022).
bladder urothelial carcinoma (3 papers, 2020 to 2022). "Immunohistochemistry and online analyses validated the functions of 4 key immune-related genes (LIG1, TBX1, CTSG and CXCL12) in bladder urothelial carcinoma." (PMID 32579540, 2020).
breast tumors (3 papers, 2014 to 2023). "TBX1 gene encodes for a T-box transcription factor 1, and its elevated level is associated with breast tumor development." (PMID 27250026, 2016). "In our research, expression of marker genes of fat browning, like UCP1, PRDM16, CIDEA, COX7A1, PGC1α, TMEM26 and TBX1, was up-regulated in adipose tissue adjacent to breast tumors." (PMID 25291184, 2014).
cervical cancer (3 papers, 2021 to 2022). A primary or metastatic malignant neoplasm involving the cervix. "The finding that TBX1 regulates stem cell properties through association with miR-200–ZEB2 suggests possible strategies for developing personalized medicine for treating patients with cervical cancer by maintaining a differentiated epithelial cell phenotype." (PMID 36418889, 2022). "Stratification of patients by TBX1 expression revealed increased overall survival for cervical cancer patients with higher TBX1 expression." (PMID 36418889, 2022). "Therefore, we speculated that TBX1 might be associated with EMT phenotypes in cervical cancer." (PMID 36418889, 2022). "Stable expression of TBX1 in HeLa cells, a cervical cancer cell line, induced strong upregulation of TBX1 levels." (PMID 36418889, 2022). "We found that TBX1 inhibited stem cell properties in cervical carcinoma cells by regulating the expression of miR-200, miR-203, and their target genes." (PMID 36418889, 2022). "Interestingly, TBX1 expression was significantly lower in cervical cancer specimens than in matched normal tissues, which was different from the case in other squamous cell carcinomas." (PMID 36418889, 2022). "In addition, it was also found that T-box transcription factor TBX1, which targets microRNA-6727-5p, inhibits cervical cancer cell growth and enhances cisplatin chemosensitivity through the AKT and MAPK pathways." (PMID 34130593, 2021).